GSK3B (glycogen synthase kinase 3 beta)
Diseases named in the same sentence as GSK3B in open-access papers (continued):
Sharing a sentence is not in itself a finding about the gene and the disease.
cancer (continued). "Since GSK3 activity is inhibited by Akt-mediated phosphorylation at Serine 21 and Serine 9 in two different isoforms namely GSK3α and GSK3β respectively, scientists believed that activation of GSK3 may likely suppress cancer progression." (PMID 25714023, 2015). "Collectively, these findings 1) indicate that a polarized cell migration-induced CD133/integrin/Src/Akt/GSK3β/β-catenin axis is required for maintenance of CSC properties, 2) establish a function for CD133 and 3) support the rationale for targeting CD133 in cancer treatment." (PMID 26515729, 2015). "Our results indicated that the phosphorylation status of AKT on Thr308 and Ser473 and the phosphorylation levels of AKT downstream targets (FKHRL1 and GSK-3β) were much higher in SP cells than those in NSP cells, suggesting that the PI3K/AKT pathway was activated in NPC cancer stem-like SP cells." (PMID 25749514, 2015). "In addition, Bmi-1 also downregulated PTEN by associating the PTEN locus and consequently activated the Akt/GSK3β pathway, ultimately induced EMT and cytoskeleton reconstruction, leading to enhanced invasiveness of cancer cells." (PMID 26452029, 2015). "The role of GSK3β in cancer cell motility has not been thoroughly studied, and the current results obtained for different types of cancers are conflicting." (PMID 24618715, 2014). "This study provides evidence that the interplay between GSK3β and β-catenin, regulated by AMPK signaling, may contribute to cancer cell proliferation and metastasis." (PMID 24666969, 2014). "No consistent changes were observed in the levels of expression of these molecules, implying that EMT is unlikely to be the mechanism by which GSK3β inhibition attenuates cancer cell migration and invasion." (PMID 23408967, 2013). "Western blot analysis confirmed the inhibitory effect of LiCl on GSK3β, as LiCl treatment resulted in increased levels of phosphorylation of serine 9 residue (pSer9) GSK3β in both the EM-TERT and AN3CA cell lines, with AN3CA cancer cells showing a higher pSer9/total GSK3β ratio." (PMID 23941783, 2013). "Since LCRMP-1 and CRMP-1 have opposite function on cancer migration and invasion, whether the function of LCRMP-1 may be regulated by GSK3β should be further studied." (PMID 22363707, 2012). "Here, we report that GSK3β can phosphorylate LCRMP-1 at Thr-628 in consensus sequences and this phosphorylation is crucial for function of LCRMP-1 to promote filopodia formation, migration and invasion in cancer cells." (PMID 22363707, 2012). "In conclusion, we show a new regulatory mechanism for GSK3β to phosphorylate an invasion enhancer LCRMP-1 and thus could further fine-tune cancer cell invasion abilities." (PMID 22363707, 2012). "Thus, our results provide evidence to support the crucial mechanism of GSK3β-dependent phosphorylation to control the LCRMP-1-mediated filopodia formation, migration and invasive abilities in cancer cells." (PMID 22363707, 2012). "A recent study of human cancer cell lines showed that ZSTK474 has potent effects on arrest of cell cycle progression through inhibition of phosphorylation or expression of Akt and/or mTORC1 substrates, such as p-GSK3β, p-mTOR, p-p70S6K and cyclin D1." (PMID 22647622, 2012). "To examine whether t-DARPP mediated GSK-3β phosphorylation in an AKT-dependent manner, we used a pharmacologic inhibitor of PI3K/AKT, LY294002, in cancer cells expressing t-DARPP." (PMID 21447180, 2011). "Chronic inhibition of GSK-3β, however, increases β-catenin and other proteins, such as adenomatous polyposis coli (APC), and this process may lead to higher incidences of cancer." (PMID 21603026, 2011). "Our results show however, that the inhibition of GSK3β or CRM1-dependent nuclear export does not result in the effective nuclear accumulation of cyclin D1 in mammalian cancer cell lines." (PMID 16503970, 2006).
cancer (continued). "Clusterin has been demonstrated to promote cancer cell survival, proliferation, and metastasis through signaling cascades such as adenosine monophosphate–activated protein kinase/mechanistic target of rapamycin/Unc-51 like autophagy activating kinase 1 and AKT/GSK3β/β-catenin pathways." (PMID 40671119, 2025). "Given the described role of GSK3B-mediated phosphorylation of T334 in facilitating HR repair regardless of BRCA1 status, we asked whether interruption of T334 phosphorylation would sensitize cancer cells to the PARPi Olaparib." (PMID 41243969, 2025). "Finally, the canonical Wnt signaling pathway, which shapes the stem cells-like properties of cancer cells and boosts proliferation, was downregulated at the level of a protein Dishevelled (DVL3) and GSK3 beta kinase (GSK3B)." (PMID 39495207, 2024). "To examine the upstream regulatory pathway, which is responsible for the anti-cancer properties of SnEA and pyrogallol in CRPC cells, we determined the inhibitory effects of SnEA and pyrogallol on the protein expression levels in the Akt/GSK-3β/β-catenin signaling pathway." (PMID 37047425, 2023). "Moreover, the expression of E-cadherin, PI3KCA, β-catenin, AKT, and GSK-3β were downregulated, indicating that IPM711 and IPM712 could reduce the proliferation and migration of cancer cells as well as the adhesion of F. nucleatum." (PMID 35308221, 2022). "GSK3B enhances the stability of DNMT1 and maintains DNA methylation and chromatin structure, which may contribute to the growth of cancer cells, while the mechanism of GSK3B and DNMT1 protein has not been clearly reported in PTOA." (PMID 35747513, 2022). "GSK-3β might contribute to the modulation of several downstream signalling pathways such as β-catenin/Snail/E-cadherin, which have been identified to regulate EMT, metastasis and the progression of various cancers." (PMID 35428758, 2022). "However, GSK3B (Glycogen Synthase Kinase 3 Beta) acts as a negative regulator in the phosphorylation of key cancer-related genes, such as APC, JUN, and CTNNB1/beta-catenin." (PMID 35645340, 2022). "Interestingly, when evaluating by size alone, we identified a greater number of patients with GSK-3β expression in T1/T2 tumors (95%CI 0.86–1.32, p = 0.523), compared to T3/T4 cancers, but without statistical significance." (PMID 33767989, 2021). "Gsk3β has been shown to regulate Hedgehog (Hh) signaling, and aberrant/constitutive activation of the canonical as well as non-canonical Hh signaling co-exists in PC and other cancers." (PMID 34206370, 2021). "Our findings identified a novel regulatory mechanism of GSK3β expression involving metabolic enzyme PGK1-coupled Hsp90, and highlighted the potential for more effective cancer treatment by selecting Hsp90 inhibitors that do not affect PGK1-regulated GSK3β expression." (PMID 34403222, 2021). "TWS119 is a specific inhibitor of GSK-3β which has been shown to inhibit cell proliferation and induce the apoptosis of human alveolar rhabdomyosarcoma cells, while it regulates epithelial-mesenchymal transition (EMT) and cancer stem cell (CSC) properties in triple-negative breast (TNB) cancer." (PMID 32526891, 2020). "GSK3β allows crosstalk between PI3K/AKT and Wnt pathways and antagonizes Wnt signaling by forming protein complexes with Axin1 and CK1 to polyubiquitinate β-catenin, the central component of canonical Wnt signaling, to inhibit cancer cell proliferation and invasion." (PMID 32117780, 2020). "However, if inhibition of GSK3-β activates Chk1, a GSK3-β inhibitor might be inhibiting cancer growth at the same time as promoting the pro-survival pathway ATR-Chk1." (PMID 31362447, 2019). "Moreover, FOXC2 can induce the expression of cancer-related genes, including AKT, GSK3β, and Snail." (PMID 29801468, 2018).
cancer (continued). "It has been demonstrated that β-catenin is clearly involved in human cancer together with other downstream components of Wnt pathway, adenomatous polyposis coli (APC), Dishevelled (Dsh), and the serine/threonine kinase GSK-3beta (GSK-3β) intracellular signaling molecules." (PMID 29966337, 2018). "As of 2011, there were no clinically available GSK3β-targeting cancer therapies." (PMID 28924210, 2017). "We found that the expression levels of the genes in the Wnt/β-catenin signaling pathway, including APC, β-catenin, TCF7L1, TCF7L2, LEF1, MMP7, C-myc, C-jun, CYCLIND1 and GSK-3β, were remarkably higher in cancer than non-cancer tissues in the p.1125Val>Ala mutant FAP family members." (PMID 29050326, 2017). "The expression levels of cell cycle proteins MMP7, C-myc, C-jun, CYCLIND1 and β-catenin degradation protein GSK-3β in the Wnt/β-catenin signaling pathway were higher in cancer than in non-cancer tissues in all the wild type and the homozygous and heterozygous variations of the patients." (PMID 29050326, 2017). "The reason behind these discrepancies is not quite clear, but indicates the complexity of GSK3β pathway which might be cancer-type specific and needs further analysis." (PMID 27602497, 2016). "Finally, we observed that BIS I induced the downregulation of many cancer stem genes, CD133 included, and we found that this new marker of EMT is highly regulated as YAP, GSK3β, and β-catenin modulated CD133 expression, addressing this gene as a co-regulated gene by these three factors." (PMID 27034169, 2016). "Furthermore, the expression levels of phosphorylated AKT, phosphorylated GSK3β, ZEB-1 and snail-1, all of which are very important for EMT process during cancer progression, were significantly up regulated in Rab3D-MCF-7 cells, but decreased in siRab3D-MDA-MB-231 cells." (PMID 25823663, 2015). "Furthermore, we indicated that Bmi-1 mediated Hes1-induced cell proliferation and migration, downregulated PTEN and activated the Akt/GSK3β pathway, consequently induced EMT and cytoskeleton reconstruction, ultimately leading to enhanced invasiveness of cancer cells." (PMID 26452029, 2015). "A recent study also showed that both GSK3β and β-catenin expression level were significantly reduced with a concomitant reduction of metastatic capability and expression of Wnt signaling pathway targeted genes in HCC cell line SMMC-7721 subjected to anti-cancer drug treatment." (PMID 25277196, 2014). "Our study suggests that EMT may not be involved in the mechanism by which GSK3β inhibition attenuates cancer cell migration and invasion." (PMID 23408967, 2013). "However, a recent study found that disruption of NF-κB activity through GSK3β inhibition did not sensitize cancer cells to gemcitabine." (PMID 23408967, 2013). "Although the exact mechanism of KOR-mediated GSK3β activation remains unclear at this time, we propose that the stimulation of KOR may activate GSK3β through inhibition of the cAMP/PKA pathway and/or activation of the JNK pathway in NSCLC, resulting in the prevention of cancer." (PMID 22343623, 2012). "The gene mutation on hot spots i.e. Thr58 of c-Myc and Ser33, Ser37, Thr41 and Ser45 of β-catenin abolishes phosphorylation by GSK3β results in preventing ubiquitination and proteasome mediated degradation of c-Myc /β-catenin has been reported in various cancers but not so far in OSCC." (PMID 20537194, 2010). "Notably, in HER2+ cells we assessed the existence of an Akt/GSK3β/β-catenin axis that can be up-modulated by DADS and that culminates in the accumulation of β-catenin inside the cell nucleus, where it is known to affect expression of genes involved in various cancer related events." (PMID 41228363, 2025).
cancer (continued). "Moreover, recent studies have elucidated the immunomodulatory properties of GSK-3β in the context of cancer, most importantly in regulating negative immune checkpoint molecules but also in directly enhancing the activity of innate and adaptive immune cells as it will be described in later sections." (PMID 34356465, 2021). "However, the role of circRNA from GSK3β gene in cancer progression has not been evaluated." (PMID 31722716, 2019). "Collectively, our findings supports the hypothesis that activation of the ATM/AKT/GSK-3β signaling pathway leading to CDK4/CDK6/cyclin D1 overexpression plays a key role in LDR-induced hormesis, and is responsible for the difference of hormesis induced by LDR in normal and cancer cells." (PMID 27708248, 2016). "GSK3β is a significant cancer control molecule; it controls the degradation of β-catenin by phosphorylating serine 33/37 of cytosolic β-catenin, and it may also be involved in crosstalk with the APC/CK1/Axin complex, which is important in cancer cell proliferation and metastasis." (PMID 24666969, 2014). "To confirm that the function of the GSK3B-53BP1 signaling pathway in HR is not an isolated phenotype in U2OS cells, we examined HR activity and sensitivity to PARPi in more cancer cell lines." (PMID 41243969, 2025). "Although not covered in the current investigation, cancer stem cell markers including CD133, CD44, DLK1, and Notch1 as well as the β-catenin/p-GSK3β signaling pathway were significantly down-regulated, and the self-renewal capacity of CSCs was suppressed." (PMID 39000345, 2024). "We used GO and KEGG analysis to analyze many cancer-related genes, including QKI, CTNNA1, GSK-3b, and RGS12, which had not been previously identified in HCC." (PMID 35068348, 2022). "Here, we do not discuss the detailed pathways regulated by GSK-3β in cancer, but we focus on discussing the relevance to PDAC of the previously proposed anti-cancer and pro-cancer roles of GSK-3β." (PMID 36430630, 2022). "In these conditions, GSK3β no longer phosphorylates PDL1 and the levels of the latter molecule rise in the cancer cell." (PMID 32850361, 2020). "For example, Wnt3a accelerates the autophagic level in neurons by modulating the GSK‐3β‐AMPK axis, but not the Wnt/β‐catenin pathway, indicating that a β‐catenin‐dependent or independent signal can generate cancer cells with a radioresistant phenotype." (PMID 31111621, 2019). "As such, inhibition of Wnt effectors β-catenin (downstream of GSK3β) or TCF/LEF, P300, or CBP would target cancer cells while insignificantly or not affecting immune cells in the TME." (PMID 31261718, 2019). "Our present study establishes that a CD133/integrin/Src/Akt/GSK3β/β-catenin axis and noncanonical Wnt signaling are activated in migrating CSCs, which contributes to a rationale for targeting CD133 in cancer treatment." (PMID 26515729, 2015). "We observed an increase in the phosphorylation of GSK3β (ser9) and stabilization of β-catenin, indicating the inhibition of the GSK3β activity by VPA treatment, but only in normal and not in cancer cells." (PMID 26413814, 2015). "To rule out any off-target effects by GSK3β inhibitors, we directly knocked down endogenous GSK3β by infecting AN3CA cancer cells and EM-TERT control cells with lentivirus carrying shRNA against human GSK3β." (PMID 23941783, 2013). "Additionally, aberrant overexpression of GSK3β has been observed in CRC patients, whereas the suppression of GSK3β expression had a negative effect on cancer proliferation." (PMID 37373005, 2023). "Furthermore, western blot analysis on PC9 and H292 cells showed that cancer-IgG knockdown under irradiation did not affect the expression of AKT, GSK3β, or DNA-PKcs proteins." (PMID 34150640, 2021). "In the absence of the Wnt signal, the phosphorylation of GSK3β at serine 9 was inhibited, which led to the degradation of β-catenin and subsequent reduced transcription of its target gene SNAIL1, which is responsible for EMT and cancer progression." (PMID 32127937, 2020).
cancer (continued). "However, low dose of perifosine (50 nM) did not affect cancer cell proliferation and the phosphorylation status of AKT, FOXO1, and GSK-3β." (PMID 31113933, 2019). "Although there was no influence on GSK3β detectable, we hypothesized that the application of PDA-66 could nevertheless induce comparable antiproliferative effects in ALL cancer cells as SB-216763 due to the similar basic molecular structure." (PMID 24502201, 2014). "Through negative modulation of GSK3β, MYCT1, Fascin actin-bundling protein 1 (FSCN1), and TFF1, miR-632 modulated the WNT/β-catenin pathway and subsequently promoted cancer cell migration, invasion, proliferation, tube formation, and endothelial cell recruitment." (PMID 35242169, 2022). "Furthermore, GL reduced phosphorylated GSK-3β (p-GSK-3β), but increased phosphorylation of Akt on serine 473 (p-Akt), possibly due to a negative feedback mechanism, as observed earlier in various cancer cell lines treated with mTOR inhibitors such as everolimus and rapamycin." (PMID 34091442, 2021).